CCR7 (C-C motif chemokine receptor 7)
Diseases named in the same sentence as CCR7 in open-access papers (continued):
Sharing a sentence is not in itself a finding about the gene and the disease.
cancer (continued). "Modulating the function of the CCL19/CCL21/CCR7 axis may hold therapeutic potential for cancer as well as many inflammation‐related diseases, and there are several clinical trials currently underway." (PMID 35702353, 2022). "The roles of CCR7 in cancers are complex, and the reports are inconsistent." (PMID 35203305, 2022). "The role of CCR7 in lymph node metastasis of cancer has been further explored." (PMID 34767139, 2022). "CCR7 and its ligands play two important but contending roles in cancer." (PMID 34361107, 2021). "Furthermore, the expression of both CXCR4 and/or CCR7 are of significant prognostic value in multiple other cancers." (PMID 34685420, 2021). "Interestingly, we found the upregulation of CCR7 in the noninvasive cancer spheroids under the synergic stimulation." (PMID 34671596, 2021). "Likewise, cancer cells that upregulate CCR7 expression are attracted by these chemokines and metastasize to lymphoid organs." (PMID 33923834, 2021). "Moreover, CCR7 has been suggested as a potential target in cancer therapy as it plays an important role in the metastasis of several cancers." (PMID 33719152, 2021). "CCR7 is also able to increase proliferation of cancer cells as well as their stemness." (PMID 34830848, 2021). "Moreover, CCR7 expression is induced by various cancer types and promotes tumor cell migration and metastasis formation in lymphoid organs." (PMID 33923834, 2021). "On one hand, the lymph node homing ability of CCR7 might promote LN metastasis of a variety of CCR7-expressing cancers, and a higher expression of the chemokines and receptor is associated with a poor prognosis." (PMID 34361107, 2021). "Antagonism of CCR7 may also yield a purposeful tool in the prevention of lymph node metastasis of CCR7 overexpressing cancers." (PMID 34361107, 2021). "An investigation of CCR7 function in chemotaxing cells may also help to understand its role in cancer metastasis." (PMID 32340161, 2020). "MOF-gated MS most efficiently enhances cancer antigen presentation, upregulates the expression of costimulatory molecules (CD40 and CD80), and promotes chemokine receptor CCR7 expression, which implies their great potential in cancer vaccines, compared with MS or MOF." (PMID 32737343, 2020). "The increase in CCR7 expression increases the migration of cancer cells." (PMID 32781743, 2020). "The activation of CCR7 on a cancer cell causes EMT and migration of cancer cells." (PMID 33076281, 2020). "One explanation could be that positive CCR7 cancer cells primarily target metastasis to lymph nodes as well as empower the immune system to eliminate escaped cancerous cells." (PMID 32340161, 2020). "In blood and lymphatic vessels CCR7 on cancer cells prevents anoikis." (PMID 33076281, 2020). "Additionally, chronic hypoxia induces the expression of podoplanins in CAF which increases the cancer cell migration in a CCR7-dependent manner." (PMID 32781743, 2020). "Hypoxia and prostaglandin E2 (PGE2) increases the expression of CCR7 on a cancer cell." (PMID 33076281, 2020). "Moreover, the chemokine receptor CCR7 is necessary for the regulation of migratory speed and plays an important role in cancer metastasis." (PMID 31555130, 2019). "Finally, CCR7 is also expressed by numerous cancer cell types and promotes cancer cell migration, dissemination, and metastasis formation in lymphoid organs." (PMID 31137829, 2019). "Furthermore, if expressed by cancer cells, CCR7 facilitates cancer cell dissemination, migration and metastasis formation in lymphoid organs." (PMID 30518137, 2018). "In our studies, we found that CCR7 was induced in cancer cells undergoing TGF‐β‐induced EMT." (PMID 28590032, 2017). "Considerable studies have focused on the potential role of CCL19/ CCR7 axis in several cancers." (PMID 29088748, 2017).
cancer (continued). "On the contrary, the high CCR7 expression on IFN-DCs did not associate with the induction of CCL21 transcripts on cancer cells, suggesting a minor role of the CCR7/CCL21 axis for the movement and function of IFN-DCs under these conditions." (PMID 28439087, 2017). "The clinical prognostic value of CCR7 has been studied in several other cancer types." (PMID 28114889, 2017). "It was reported that CCL19/CCR7 responded for the migration of cancer calls via the AKT pathway." (PMID 28378417, 2017). "These included genes involved in cell death and survival processes (BCLAF1, CFLAR, CASP1, and XIAP), genes associated with proliferation-driving transcription or cancer (KLF4, LEF1, SOX4, ID3), and genes associated with inflammation (CD28, CCR7, CX3CR1 and IFNG)." (PMID 28407008, 2017). "CCR7 has also been shown to mediate lymphatic dissemination of cancer cells." (PMID 28590032, 2017). "For example, CCL21 (CC chemokine ligand 21) and CCL19 (CC chemokine ligand 19) recruit antigen-presenting dendritic cells and naïve T-cells to the lymph nodes and are thought to play a role in lymph node metastasis of CCR7 (CC chemokine receptor 7)-expressing cancer cells." (PMID 28841151, 2017). "CCL21 could promote chemoresistance in cancer cell by its receptor CCR7; hence, CCR7 may be seen as a target in the future cancer therapy." (PMID 27057280, 2016). "The activation of TGF-β-activated protein kinase 1 (TAK1) may up-regulate CCR7 expression and increase lymphatic invasion ability of cancer cells." (PMID 28036019, 2016). "Interestingly, studies have identified the up-regulation of CCR7 in various types of malignant tumors, such as breast cancer, gastric cancer, and prostate cancer, and have revealed its function in promoting lymph node metastasis." (PMID 26667143, 2015). "Nonetheless, CCL21/CCR7 may facilitate cancer cell invasion via increasing MMP secretion and enhancing cell motility." (PMID 25798926, 2015). "However, all studies interfering with the CCR7 axis in humans to treat cancer and metastasis are still in very early stages." (PMID 25254213, 2014). "Interestingly, the treatment with a blocking anti-CCR7 mAb abrogated both lamellipodia and invadopodia formation, further supporting the role of CCR7-mediated signaling in cancer progression." (PMID 24305507, 2013). "Because cell fusion has been linked to cancer metastasis and M13HS-2 and M13HS-8 were positive for CCR7 expression we thus investigated whether the CCL21/CCR7 axis could be activated in these hybrid cell lines." (PMID 23667660, 2013). "Although the role of chemokines and their receptors in human cancers is complex, the chemokine receptors CCR7 and VEGF-C may be critical in determining lymph node metastasis in these types of tumors." (PMID 23761820, 2013). "The chemotactic SLC/CCR7 interaction may be a possible mechanism for induction by cancer cells of lymph node metastasis and tissue invasion." (PMID 24040244, 2013). "CCR7 is known to play an important role in cancer metastasis." (PMID 22251626, 2012). "The development of CCR7 antagonists will allow investigators to determine whether such agents can potentially be beneficial to cancer therapy." (PMID 24212647, 2011). "The chemokine receptors CXCR4 and CCR7 play an important role in cancer invasion and metastasis." (PMID 20181250, 2010). "This targeting mechanism of ExoDS may be attributed to a variety of membrane receptors like integrin α and β chains (αMβ2), ICAM-1, MFG-E8, TNF, FasL, CD86, CD80, CD40, CD83, MHC-I, MHC-II, NKG2D, IL-15Rα, CD21, CD11c, and CCR7, which help mDC-derived exosomes identify cancer cells." (PMID 38903193, 2024). "Moreover, evidence suggested that CCR7 might drive immune cell migration into the lymph node, providing a possible role of CCR7 in regulating the cancer cell metastasis." (PMID 37600570, 2023). "Therefore, both Ccr7 and Dhps could affect the T lymphocyte proliferation pathway that plays a critical role in the cancer’s progression." (PMID 35180880, 2022).
cancer (continued). "Therefore, the increased expression of CCR7 has an anti-cancer effect via cytotoxic TIL in tumors." (PMID 35123499, 2022). "Targeting CCR7 by low molecular weight compounds is proposed and, by doing so, may play a major role in reducing the spread of cancer cells to lymph nodes, which is an important reason for cancer related deaths." (PMID 34770763, 2021). "Interestingly, expression of CCR7 was even lower on CD8+ Tc cells of cancer patients." (PMID 32082401, 2020). "Hence, CCR7 could become a predictive marker for a number of cancers, including colorectal liver metastasis." (PMID 31991604, 2020). "Many different chemokine pathways are known and their role in cancer has been completely and well reviewed by others; therefore, in this review we focus on chemokine axes involved in lymphatic metastasis: the chemokine receptor 7 (CCR7) with its ligands CCL19 and 21 and the CXCR4/CXCR12 axis." (PMID 25254213, 2014). "Therefore, the results suggest that CCR7 signaling could be activated and affect cancer cells themselves by inducing strong expression of CCL21." (PMID 22251626, 2012). "Of note, CCR7 has been found to be expressed by many epithelial cancers, including those of the breast, stomach, and colon, suggesting that its role in increasing LN metastasis may be generalizable to other cancers." (PMID 24212647, 2011). "Following a 4-hour incubation with cancer cells, we stained the PBMCs to identify CD45+ CD3+ CD8+ CCR7+ T-cells (CD8+ TCM) and measured their expression of PD-1 and CD107a." (PMID 40346531, 2025). "The CCL19/C-C motif chemokine receptor (CCR) 7 axis poses an anti-cancer property that both CCL19+ DCs and CCR7+ DCs augment CD8+ T cell immunity." (PMID 39114657, 2024). "CCR7+ DC-CD8+ T cell engagement and their augmentation by ICB was confirmed across a range of human cancers." (PMID 38267413, 2024). "Compared to Mo‐DC from cancer patients, healthy Mo‐DC expressed higher levels of HLA‐DR, CD86, CD83, and CCR7." (PMID 38351552, 2024). "A recent study using analysis of the cancer genome atlas (TCGA) and in vitro transwell migration assays suggested CCL19/CCR7 directly drives T regulatory cell (Treg) migration to gastric cancer, providing a role for the signaling axis in immunosuppression." (PMID 38786066, 2024). "The results of the IHC assay and qPCR assay both showed that the expression levels of CCR1, CCR5, and CCR7 were significantly lower in HCC tissues, compared with para-carcinoma tissues." (PMID 38552222, 2024). "We observed that the expression levels of CCR1, CCR2, CCR5, and CCR7 were significantly lower in the HCC tissues in TCGA LIHC dataset and GSE14520 dataset, compared with para-carcinoma tissues." (PMID 38552222, 2024). "We demonstrate the presence of CD103+ tissue resident memory T cells (TRM), CCR7+ central memory T cells, and CD57+ terminally differentiated effector cells across all HPB cancers, with simultaneous expression of multiple co-inhibitory checkpoint receptors." (PMID 36798126, 2023). "Previous research has shown that the CCL21/CCR7 axis promotes EMT and metastasis in cancer cells by activating the MEK/ERK1/2 signaling pathway." (PMID 36829431, 2023). "Conditional medium obtained from several cancer cell cultures activated LXR-α signaling on the dendritic cell surface, thereby decreasing CC chemokine receptor-7 (CCR7) expression in these DCs93." (PMID 37653037, 2023). "Analyzing expression of these markers by CD8+ T cells, we observed a significant relative reduction of CCR7+ and CD62L+ CD8 cells in cancer patients." (PMID 38019346, 2023). "For instance, STAT3 transcriptionally regulates CCR7 to promotes cancer, while miR-4500 inhibits STAT3 expression by targeting the STAT3 3′-3UTR region and thus suppressed cancer development." (PMID 36227136, 2022). "Several chemokine receptors, namely CCR4, CCR7, CCR9, and CXCR4, are substantially expressed in oncovirus-induced cancer cells." (PMID 35159113, 2022).
cancer (continued). "Nevertheless, it is evident that CCR7 and VEGF are commonly co-expressed in a variety of different cancers, which are poor prognostic factors typically resulting in lymphatic invasion and reduced patient survival." (PMID 35203305, 2022). "A previous link between CCR7 expression and VEGF-C expression has been noted for other cancers and was investigated in A549 cells." (PMID 35203305, 2022). "Our team discovered that cancer-originated DNA can activate the CXCL12-CXCR4 and CCL21-CCR7 axes in HCC cells, while sinoline treatment reduced the expressions of CXCL12, CXCR4, CCL21, and CCR7 in HCC cells." (PMID 35860597, 2022). "However, CCR7 could also enhance proliferation and stemness of cancer cells." (PMID 35123499, 2022). "CCR7 binds to the CCL19 and plays an important role in the trafficking of immune cells as well as cancer metastasis." (PMID 36199375, 2022). "Using flow cytometry of human cancer specimens, we examined the heterogeneity of human TI-Tregs using effector/memory markers CD45RA and CCR7." (PMID 33627663, 2021). "Congruently, in clinical studies CCR7 expression correlated with LVI, LN metastasis and poor outcome in various cancer types such as gastric cancer, pancreatic cancer, non-small cell lung cancer, colorectal carcinoma, and cervical cancer." (PMID 34685565, 2021). "Next, we observed significant associations of the expression levels of CD20 with CCR6 (total rho=0.62), CCR7 (total rho=0.79), and CXCR5 (total rho=0.73) in most cancer types." (PMID 35069521, 2021). "MANOVA on these genes reveals that this combined set of 7 genes (MYC, CD40LG, CCL4, IL7, TCF4, CCR7 and FASLG) is together statistically significantly reliant on both time post-exposure (p = 0.042) and cancer type (p < 0.001)." (PMID 33941218, 2021). "CCL21/CCR7 generally promotes the cell cycle, MAPK, JAK/STAT, NFκB, PI3K/AKT, and Rho A signals in many cancer cells with cell growth and migration." (PMID 34948416, 2021). "In cancer progression and metastasis, the expression of chemokine receptor 4 (CXCR4) and chemokine receptor 7 (CCR7) is of particular importance." (PMID 34685420, 2021). "The chemokine receptors CCR7 and CXCR4, which are expressed by invading cancer cells, bind to secreting chemokines such as CCL21 and CXCL12, to recruit more cancer cells towards lymphatic vessels." (PMID 33172072, 2020). "However, this axis may also have pro-cancer properties if CCR7 is located on a cancer cell." (PMID 33076281, 2020). "While CCL14 and XCL1 have shown only good prognostic value, other chemokines such as CCL5, CCL20/CCR6, CCR7, CXCL1, CXCL8, and CXCL12/CXCR4 have consistently played the role of poor prognostic markers in different kinds of cancer." (PMID 31991604, 2020). "We also noted reduced surface expressions of CD62L, CD28, CCR7, and CD127 on cancer patients’ T cells." (PMID 33230147, 2020). "In order to determined role of some factors which are involved in cancer progression IDO, FASL, VEGF, SOCS1 and CCR7 were measured." (PMID 29299026, 2017). "CCL19 is highly expressed in human cancer cells, and ligand CCL19 binding to CCR7 induces actin polymerization and pseudopodia formation." (PMID 29088748, 2017). "In these malignancies, interaction of CCR7 with CCL21 drives migration and invasion of CCR7+ cancer cells into lymph nodes similarly to normal homing." (PMID 28416768, 2017). "Some genes are important factors in the immune system of cancer patients, such as CCL2, CCL20, CCL5, CCR7, IFNG and P450 family." (PMID 28384236, 2017). "The chemokine receptor CCR7 and its chemokine ligands CCL21 and, less so, CCL19, recruit circulating metastatic cancer cells to lymphatic tissue." (PMID 28841151, 2017). "Our results demonstrated that in the presence of ionizing radiation either RKO or SW1463 cancer cells increased mRNA expression levels of the macrophage pro-inflammatory markers TNF, IL6, CCL2 and CCR7 as well as of the anti-inflammatory marker CCL18." (PMID 27513864, 2016).
cancer (continued). "C-C chemokine receptor 7 (CCR7) interacts with its ligand, chemokine ligand 21(CCL21), to mediate metastasis in some cancer cells lines." (PMID 27505247, 2016). "The mRNA and protein expression levels of CCR7, CXCR4 and VEGF-C were all significantly higher in the cancer samples compared with those in the adjacent normal tissue." (PMID 23761820, 2013). "It was demonstrated that the expression levels of CCR7, CXCR4 and VEGF-C mRNA and protein were all significantly higher in the cancer specimens compared with those in the adjacent normal tissue." (PMID 23761820, 2013). "A search for alternative biomarkers suggested that T-cell differentiation, as measured by expression on CD8+ T cells of CCR7, a chemokine receptor for CCL19 and CCL21, discriminated cancer patients from normal controls." (PMID 23730621, 2013). "The expression levels of CCR7, CXCR4 and VEGF-C mRNA in the cancer samples were all significantly higher than those in the adjacent normal tissue." (PMID 23761820, 2013). "CCR7 mediates SCCHN metastasis by activating integrin αvβ3, which facilitates adhesion of cancer cells to or migration through the extracellular matrix." (PMID 24259307, 2013). "Normally, CCR7 activity is regulated by CCL19 and CCL21, which is secreted by cancer cells themselves and allows cancer cells to migrate to the lymphoid tissues." (PMID 22251626, 2012). "In contrast, CCR7− cDC1s further contribute to the acquisition of the CD8+ T cell effector programme and support their tumoricidal activity through the secretion of IL‐12, contributing to productive anti‐cancer immunity." (PMID 40878038, 2025). "We therefore tested an alternative Ccr7 inhibition approach using navarixin, a small molecule negative allosteric modulator of Ccr7, Cxcr1, and Cxcr2 that has been studied in clinical trials for airway disease and cancer indications." (PMID 39969509, 2025). "Conversely, CXCL16 and IL-15 expressing CCR7+ DCs may recruit and sustain CXCR6+ cytotoxic T cells crucial in cancer immunosurveillance." (PMID 38267413, 2024). "Interestingly, we noted that high cell membrane CCR7 expression was a prognostic protective factor in BLCA, which is consistent with the results of pan-cancer research." (PMID 38762550, 2024). "Moreover, the CCR7 chemokine axis, which encompasses CCL21 and CCL19, has emerged as a promising target for cancer immunotherapy, demonstrating potential as a target for therapeutic intervention." (PMID 39505867, 2024). "Notably, miR-21-5p directly targets CCR7, suppressing downstream STAT3 and NF-κB signaling—crucial players in cancer development." (PMID 38542153, 2024). "Additionally, the intricate chemokine receptor 7 (CCR7) chemokine axis, characterized by chemokine ligand 21 (CCL21) and CCL19, has emerged as a promising avenue in cancer immunotherapy." (PMID 37944262, 2023). "The combination of modifications in terms of DC activation (e.g., CD40L and caTLR4), DC migration to lymph nodes (e.g., CCR7), and knockout of PDL1-driven immunosuppression could dramatically increase DC vaccine efficacy in cancer therapy." (PMID 38136940, 2023). "The results suggest a link between inflammatory mediators, CCR7, EMT and cancer progression." (PMID 35203305, 2022). "It should be noted that the role of CCL19/CCR7 in NSCLC appears to be complex, and post-transcriptional regulation of these genes may be important in the progression and metastasis of this cancer." (PMID 35160116, 2022). "This may also be the reason why relatively few statistically significant results were obtained regarding the relationship between the expression level of CCR7/CCL19 mRNA, study miRNAs, and cancer features." (PMID 35160116, 2022). "Cancer treatments or what changes such treatments would have on CCR7 functions is not covered in this review; however, it is noteworthy that CCR7 appears to play a significant role in cetuximab resistance in colorectal patients." (PMID 35203305, 2022).